PHKG2 (phosphorylase kinase catalytic subunit gamma 2)
Description:
Catalytic subunit of the phosphorylase b kinase (PHK), which mediates the neural and hormonal regulation of glycogen breakdown (glycogenolysis) by phosphorylating and thereby activating glycogen phosphorylase. May regulate glycogeneolysis in the testis. In vitro, phosphorylates PYGM.
Synonyms: GSD9C
Tractability: Small molecule: a structure with a bound ligand is known; a high-quality ligand is known; it has a high-quality binding pocket; it belongs to a druggable protein family. PROTAC: ubiquitination databases record sites on it; its protein half-life has been measured; a small molecule that binds it is known.
Target class: CAMK protein kinase group; Kinase; Enzyme; Protein Kinase; CAMK protein kinase PHk family
Gene: Protein-coding gene on chromosome 16 (30,748,293 to 30,761,176, forward strand). Ensembl gene ENSG00000156873.
Subcellular location (Human Protein Atlas): Cytosol
Pathways (Reactome):
Metabolism: Glycogen breakdown (glycogenolysis)
Gene Ontology:
Molecular function: phosphorylase kinase activity; protein binding; protein serine/threonine kinase activity; tau-protein kinase activity; ATP binding; calmodulin binding; enzyme binding; protein kinase activity
Biological process: generation of precursor metabolites and energy; glycogen catabolic process; glycogen metabolic process; positive regulation of glycogen catabolic process; protein phosphorylation; signal transduction
Cellular component: cytosol; cytoplasm; phosphorylase kinase complex
Genetic constraint (gnomAD): Loss-of-function variants: 30 observed, 46.43 expected, observed/expected ratio (o/e) 0.65, 90% interval 0.48 to 0.88. The upper end of that interval is the gene's LOEUF score, 0.88, which puts it in group 3 of 6, group 1 being the genes least tolerant of losing a copy. Missense variants: 498 observed, 554.73 expected, observed/expected ratio (o/e) 0.9, 90% interval 0.83 to 0.97. Synonymous variants: 220 observed, 216.63 expected, observed/expected ratio (o/e) 1.02, 90% interval 0.91 to 1.14.
Gene-disease validity (ClinGen):
ClinGen rates the evidence that PHKG2 causes each of these diseases.
glycogen storage disease IXc (autosomal recessive): Definitive.
Homologues: Orthologues: macaque PHKG2 (99% identical), dog PHKG2 (96% identical), pig PHKG2 (96% identical), rabbit PHKG2 (95% identical), chimpanzee PHKG2 (94% identical), mouse Phkg2 (94% identical), guinea pig PHKG2 (93% identical), rat Phkg2 (93% identical), tropical clawed frog phkg2 (69% identical), zebrafish phkg2 (69% identical). Paralogues in human: PHKG1 (60% identical), CAMK2D (33% identical), CAMK2B (33% identical), CAMK2G (32% identical), CAMK2A (32% identical), CAMK1D (29% identical), CAMK1G (29% identical), PNCK (29% identical), CAMK1 (28% identical), DCLK2 (27% identical), DCLK3 (27% identical), DCLK1 (27% identical), and 10 more.
Diseases named in the same sentence as PHKG2 in open-access papers:
PHKG2 is named in the same sentence as 32 diseases in open-access papers, as found by Europe PMC text mining. Sharing a sentence is not in itself a finding about the gene and the disease. The quoted sentences say what the papers report.
glycogen storage disease (6 papers, 2017 to 2025). "Among other genes, AMIGO2 and PHKG2 are associated with gastric adenocarcinoma and glycogen storage disease, respectively." (PMID 38764094, 2024). "People get glycogen storage disease type IXc, a rare and severe phenotype of glycogen storage disease, when PHKG2 is defective." (PMID 36747547, 2023). "Liver phosphorylase b kinase (PhK) deficiency (glycogen storage disease type IX), one of the most common causes of glycogen storage disease, is brought by mutations in the PHKA2, PHKB and PHKG2 genes." (PMID 28410206, 2017). "GSDIX is a group of glycogenoses caused by hepatic phosphorylase kinase deficiency, a hexadecameric enzyme comprising four copies each of four unique subunits encoded by four different genes; PHKA1, PHKA2, PHKB, and PHKG2." (PMID 34946936, 2021).
breast carcinoma (5 papers, 2014 to 2022). "PHKG2 is a useful diagnostic biomarker for multiple cancers, including breast cancer and endometrial cancer." (PMID 35866375, 2022). "Previous studies have found that PHKG2 expression is elevated in human breast cancer cells, indicating that it might be a useful diagnostic biomarker." (PMID 33989111, 2021). "The mRNA expression from the PHKG2 gene was performed by real-time PCR using RNA extracted from breast cancer cell lines; we found that the level of PHKG2 mRNA expression was lowest in the non-tumorigenic cell line MCF10A, but elevated in the other BC cell lines." (PMID 28410206, 2017). "LncRNA LIPE-AS1 was co-expressed with 5 ferroptosis-related genes (HRAS, PHKG2, MAPK14, EGLN2, and GPX4), including 4 ferroptosis driver and 1 ferroptosis suppressor, and we found that LIPE-AS1 was a protective factor for breast cancer patients’ prognosis." (PMID 34164433, 2021). "Screening of breast cancer cell lines showed that the mRNA expression levels for the PHKG2 and DPEP1 were lower in non-tumorigenic mammary epithelial cell MCF10A, but elevated in other cell lines." (PMID 28410206, 2017).
glycogen storage disease type IXc (4 papers, 2017 to 2025). "Pathogenic mutations in the PHKG2 are associated with a very rare disease—glycogen storage disease IXc (GSD-IXc)—and are characterized by severe liver disease." (PMID 35549678, 2022). "In the Ketosis example, only two diseases were associated with onset data: Methylmalonic aciduria, cblA type (caused by MMAA) annotated as both ‘neonatal’ and ‘infantile’ and Glycogen storage disease IXc (caused by PHKG2) which also an infantile disease according to HPO." (PMID 28715999, 2017).
Cirrhosis (3 papers, 2025). A chronic disorder of the liver in which liver tissue becomes scarred and is partially replaced by regenerative nodules and fibrotic tissue resulting in loss of liver function. "It has been observed that liver fibrosis/cirrhosis is highly prevalent in patients with GSD IXc (caused by mutations in the PHKG2 gene), with a rate of 95.8%." (PMID 40211049, 2025). "Unlike GSD IXa and GSD IXb, GSD IXc [due to deficiency of the γ subunit of phosphorylase kinase (PK) enzyme, encoded by the PHKG2 gene) is a more severe disorder with a high prevalence of liver fibrosis that can progress to cirrhosis during childhood and the need for LT." (PMID 40743267, 2025). "However, some genotypes, such as PHKG2, may contribute to the development of cirrhosis." (PMID 40428406, 2025).
papillary thyroid cancer (3 papers, 2018 to 2023). "Methylation of PHKG2 may be associated with mutation of the BRAF/RAS oncogene in papillary thyroid cancer." (PMID 34170849, 2021). "The reported research showed that PHKG2 was frequent epigenetic hypermethylation in papillary thyroid cancer." (PMID 36747547, 2023). "Kikuchi et al26 identified multiple genes (HIST1H3J, POU4F2, SHOX2, PHKG2, TLX3 and HOXA7) with frequent epigenetic hypermethylation in papillary thyroid cancer, which might function as potential biomarkers." (PMID 30039914, 2018).
endometrial cancer (2 papers, 2022 to 2024). Primary or metastatic malignant neoplasm involving the endometrium (mucous membrane that lines the endometrial cavity). "Phosphorylase kinase G2 (PHKG2) can be used as a biomarker for thyroid cancer, endometrial cancer, renal clear cell carcinoma and colorectal cancer." (PMID 38743344, 2024).
lung carcinoma (2 papers, 2024 to 2025). "Supporting this, a recent study in lung cancer revealed that radiosensitive tumors exhibited high PHKG2 and low NRF2 expression, whereas radioresistant tumors displayed the inverse profile." (PMID 40885710, 2025). "The 8 FRGs (ACSL3, FADS2, GLS2, HSF1, PANX1, PHKG2, VDAC2, and CDKN1A) that we selected to be associated with the diagnosis and prognosis of lung cancer have been shown to play important roles in cancer and tumor immunity." (PMID 38743344, 2024).
Mauriac syndrome (2 papers, 2021 to 2024). A complication of poorly controlled type 1 diabetes mellitus in children characterized by linear growth impairment, glycogenic hepatopathy, and Cushingoid features. "In 2016, a heterozygous genetic mutation in PHKG2 providing a subunit of glycogen phosphorylase kinase enzyme complex was discovered in a patient who was diagnosed with Mauriac syndrome." (PMID 39156415, 2024). "The PHKG2 mutation is the only mutation discovered when cross-referenced with the online Mendelian inheritance in a man with a genetic predisposition for Mauriac syndrome." (PMID 39156415, 2024).
non-small cell lung carcinoma (2 papers, 2024 to 2025). A group of at least three distinct histological types of lung cancer, including non-small cell squamous cell carcinoma, adenocarcinoma, and large cell carcinoma. "Our research aims to highlight the regulation of radiotherapy-induced ferroptosis in non-small cell lung cancer (NSCLC) via the NRF2/PHKG2 axis-mediated mechanism." (PMID 39169204, 2024). "In non-small cell lung cancer (NSCLC), targeting and regulation of the NRF2/PHKG2 axis promotes ferritinophagy, increases intracellular iron levels, and enhances the radiosensitivity of NSCLC cells through mitochondrial stress-dependent ferroptosis." (PMID 40093329, 2025).
breast tumors (1 paper, 2023). "We obtained 5 prognosis-related genes, as the key biomarkers by Lasso-cox analysis (FBXL19, HAGHL, PHKG2, PKMYT1, and TXNDC17), all of which were significantly upregulated in breast tumors." (PMID 36747547, 2023).
cervical cancer (1 paper, 2022). A primary or metastatic malignant neoplasm involving the cervix. "A previous research group established a 4-gene signature related to ferroptosis of cervical cancer patients (TFRC, ACACA, SQLE and PHKG2)." (PMID 36313765, 2022).
Hypotonia (1 paper, 2022). Hypotonia is an abnormally low muscle tone (the amount of tension or resistance to movement in a muscle). "Hypotonia and motor delay can be rarely associated to PHKB and PHKG2 mutations." (PMID 35725468, 2022).
liver cirrhosis (1 paper, 2022). "Among the GSD IX subtypes, the progression to liver cirrhosis had initially been described only in patients affected by PHKG2 mutations." (PMID 35725468, 2022).
lung adenocarcinoma (1 paper, 2023). A carcinoma that arises from the lung and is characterized by the presence of malignant glandular epithelial cells. "In lung adenocarcinoma, PHKG2 is involved in the process of ferroptosis which prevents tumor development." (PMID 36747547, 2023).
renal tubular acidosis (1 paper, 2022). A group of genetic disorders of the kidney tubules characterized by the accumulation of metabolically produced acids with elevated plasma chloride, hyperchloremic metabolic acidosis. "Conversely, individuals affected by PHKA2 and PHKG2 mutations can display renal tubular acidosis and tubulopathy with secondary development of rickets in a patient with GSD type IXc." (PMID 35725468, 2022).
tumor (10 papers, 2021 to 2025). "The expression and mutation profiles of IFNG, KEAP1, and PHKG2 may serve as indicators of the tumor mutational burden (TMB) in OV, indicating their potential utility as predictive biomarkers for tumor response and prognosis." (PMID 40744688, 2025). "In the TCGA-STAD dataset, AKR1C2 exhibited reduced expression in the tumor group; conversely, HCAR1, KRAS, and PHKG2 showed increased expression in the tumor group." (PMID 41050072, 2025). "PP1 activity in tumor tissues was elevated in the Erastin-treated group, while PHKG2 knockdown diminished this activation." (PMID 40885710, 2025). "Immunohistochemistry (IHC) analysis confirmed higher PHKG2 expression in tumor tissues compared to adjacent normal tissues (p < 0.001)." (PMID 40885710, 2025). "Both in vitro and in vivo, PHKG2 overexpression significantly suppressed tumor growth and increased lipid peroxidation levels." (PMID 40885710, 2025). "Administration of Erastin significantly reduced tumor volume in xenografted mice, but this anti-tumor effect was attenuated when PHKG2 was silenced." (PMID 40885710, 2025). "Our study highlights the potential of IFNG, KEAP1, and PHKG2 as predictive markers for T cell infiltration and the tumor microenvironment status in OV." (PMID 40744688, 2025). "Clinically, PHKG2 expression correlates inversely with tumor stage and serves as an independent protective factor." (PMID 40885710, 2025). "Collectively, these findings highlight PHKG2 as a regulatory “switch” that tilts tumor cells toward ferroptotic death by inactivating the NRF2/GPX4 axis." (PMID 40885710, 2025). "In the RNAseq dataset, both ACSL3 and PHKG2 were expressed higher in the post-radiotherapy tumor tissues than in the pre-radiotherapy tumor tissues." (PMID 39169204, 2024). "In summary, three genes (ACACA, SQLE, and PHKG2) in the newly developed signature have established roles in the protection of tumor cells against ferroptosis, whereas TFRC has the opposite effect." (PMID 33989111, 2021). "Moreover, high TMB was associated with increased T cell infiltration and exhibited a distinct gene signature, which highlights the potential of IFNG, KEAP1, and PHKG2 as predictive markers for T cell infiltration and the tumor microenvironment status in OV." (PMID 40744688, 2025). "The research also demonstrated the transcriptional inhibition of PHKG2 by NRF2 and created in situ transplantation tumor models of NSCLC to examine the role of NRF2/PHKG2 axis in NSCLC radiosensitivity and resistance in vivo." (PMID 39169204, 2024). "The experimental results showed that the knockdown of PHKG2 significantly improved the radioresistance in NSCLC, as demonstrated by the significantly higher tumor growth rate and larger experimental endpoint tumor size under radiotherapy treatment." (PMID 39169204, 2024). "However, the study’s focus on a limited number of gene regulatory pathways necessitates further investigation, including whether NRF2’s inhibitory effect on PHKG2 transcription applies to other tumor samples and the roles of other genes in radiation resistance regulation." (PMID 39169204, 2024). "FADS2, PHKG2, and VDAC2 were significantly related to tumor invasion depth." (PMID 38743344, 2024). "ATP5G3, PHKG2 and PRKAA2 may be highly expressed in tumor cells, but the difference was not statistically significant (cor > 0, P > 0.05)." (PMID 34170849, 2021).
cancer (9 papers, 2013 to 2025). A tumor composed of atypical neoplastic, often pleomorphic cells that invade other tissues. "Beyond its redox-regulatory role, PHKG2 has emerged as a broader ferroptosis-associated gene and favorable prognostic marker in multiple cancer types." (PMID 40885710, 2025). "Identifying specific genes involved in cancer cell survival and apoptosis, such as PHKG2, creates new opportunities to develop personalized treatments to enhance cancer patient survival rates." (PMID 39169204, 2024). "Meanwhile, four of the FRGs, ATP5MC3, HMGCR, CARS1, and PHKG2, are strongly related to the competitive endogenous RNA (ceRNA) network, which has become more and more popular in cancer research nowadays." (PMID 34868393, 2021). "Furthermore, our analysis identified three ferroptosis‐related genes, including IFNG, KEAP1, and PHKG2, as key biomarkers in prognosis prediction and potential targets for OV cancer therapy." (PMID 40744688, 2025). "Importantly, this work underscores the functional plasticity of metabolic enzymes in cancer biology—PHKG2, a classical glycogen-related kinase, is reprogrammed here to regulate stress-responsive transcription networks." (PMID 40885710, 2025). "Nevertheless, recognizing the importance of understanding the roles of FAGs and PHKG2 and their regulatory mechanisms in NSCLC radiation resistance holds rich potential for further investigation and development to enhance cancer treatment outcomes." (PMID 39169204, 2024). "In conclusion, previous studies have reported that PHKG2, PEBP1 and NCOA4 are positive regulators that promote ferroptosis in some kinds of cancers, whereas the remaining two genes (ACSL3 and CISD1) suppress ferroptosis in cells." (PMID 34115610, 2021). "A similar fraction of cancer samples showed high methylation in each gene (2/20 for HIST1H3J, 8/20 for POU4F2, 4/20 for SHOX2, 5/20 for PHKG2, 6/20 for TLX3, and 4/20 for HOXA7)." (PMID 24367375, 2013). "Levels of TFRC (P<0.001), PHKG2 (P=0.005), FADS2 (P<0.001), and NOX1 (P=0.011) mRNA relative expression were higher in cancer cells than in immune cells, whereas levels of ALOX5 (P<0.001) mRNA relative expression were lower in cancer cells than in immune cells." (PMID 35866375, 2022). "The PHKG2 and RNF40 genes are either overlapping or close to the sequences of SCAR marker BC13-4, while SCAR marker BC10-1 is in the intron and overlap the DPEP1 gene, suggesting that alterations in the expression of these genes could contribute to cancer progression." (PMID 28410206, 2017). "The increased TFRC, PHKG2, FADS2, NOX1, and reduced ALOX5 levels in LUSC tissues were reported in the present study, and scRNA-seq analysis showed that the levels of the five dysregulated genes were mainly influenced by cancer cells rather than immune cells." (PMID 35866375, 2022).
PHKG2 also shares sentences with these, for which no sentence is quoted: Glycogen storage disease IXc (2 papers); liver fibrosis (2); colorectal cancer (1); gastric adenocarcinoma (1); head and neck squamous cell carcinoma (1); hepatic (1); liver disease (1); metabolic disease (1); Methylmalonic aciduria (1); Mucopolysaccharidoses (1); myopia (1); Obesity (1); renal clear cell carcinoma (1); rickets (1); thyroid cancer (1).